CD69 (CD69 molecule)
Diseases named in the same sentence as CD69 in open-access papers (continued):
Sharing a sentence is not in itself a finding about the gene and the disease.
tumor (continued). "It was also reported that the population of CD8+, CD45RO+, PD-1+, TBET+, EOMES+ T cells increased after treatment only in TILs if compared to the peripheral blood, and that the gene expression signature of EOMES+, CD69+, CD45RO+ T cells was associated with greater tumor shrinkage in both therapies." (PMID 32265933, 2020). "Nonetheless, HLA-DR was detected on both CD69+ and CD69− ILCs in the tumor." (PMID 32341343, 2020). "Moreover, Yanmei and colleagues identified induced CD69+CD4+CD25− T cell population along with tumour progression in an orthotopic hepatic tumour mouse model." (PMID 31907005, 2020). "Furthermore, NK cells present in the tumor of Caspase-1-deficient hosts expressed higher levels of NK cell activation markers NKG2D, Granzyme B (GZB), CD69 and CD98." (PMID 33042810, 2020). "Notably, tumor-derived pDCs responded to TLR stimulation with upregulation of CD69, CD86, and CD83 after 4 h." (PMID 33013879, 2020). "Furthermore, these infiltrating T cells in tumor had enhanced activation levels, as indicated by their increased CD69 expression." (PMID 32724476, 2020). "However, we found that the CD45(−) exosome fraction suppressed T cell activation independently of tumor stage, indicating that CD69 suppression is a more stationary effect, which is induced by all TEX." (PMID 32708274, 2020). "CD69, a type II glycoprotein known to regulate inflammation through T-cell migration and retention in tissues, plays an important role in inducing the exhaustion of tumor-infiltrating T cells." (PMID 32963529, 2020). "Interestingly, enhanced anti-tumor immunity against MHC class I tumors (RMA-S ad RM-1) was reported in CD69 knockout mice and mice treated with an anti-CD69 antibody." (PMID 31114758, 2019). "Interestingly, the level of expression of PDL1 directly correlated with the expression of CD69 on the tumor infiltrating CD8+cells, suggesting the instauration of a T cell dependent mechanism of PDL1 upregulation and immune escape." (PMID 31214178, 2019). "Indeed, most TIL subpopulations had attributes of tissue residency, including low S1pr1 and Klf2 expression and high Cd69 expression, contrasting with Arm and most tumor dLN clusters." (PMID 31801070, 2019). "In tumor-draining and peptide-draining axillary LN, CD69 was higher on L-selectin sufficient T cells whereas in tumor-draining and peptide-draining inguinal LN, CD69 was upregulated equally." (PMID 31249570, 2019). "Additionally, a high proportion of tumor-infiltrating T cells in the treatment groups expressed CD69, a marker of T cell activation." (PMID 31781498, 2019). "Indeed, CD8+CD69+ T cells are immunoregulatory cells that are known to promote tumor progression by inducing the production of indoleamine 2,3, dioxygenase (IDO)." (PMID 31114758, 2019). "Therefore, L-selectin enhanced T cells respond to the presence of a tumor differently to L-selectin knockout T cells and upregulate CD69 both inside the tumor and at sites of antigen presentation and priming in secondary lymphoid organs." (PMID 31249570, 2019). "However, Treg expression of CD69 was near 100% in unaffected colon tissue and only slightly lower in the tumor." (PMID 30651930, 2018). "Tumour infiltrating lymphocytes have higher expression of CD69 and lower expression of CCR7." (PMID 29587679, 2018). "However, the mouse model of removing CD69 showed strong antitumor properties, indicating that the body is self-limiting in eliminating exogenous infection and tumor cells immune response." (PMID 29643992, 2018). "In contrast, both the lung and tumor compartments harbored high frequencies of CD69+CD103+ cells." (PMID 30505306, 2018). "Similarly, for sdCAR-T cells, a remarkable upregulation of CD69, an activation marker presented on T cell surfaces, was observed only in the presence of cognate tumor cells (MSLN+ K562) and the switch molecule FHBM." (PMID 29558951, 2018). "There was downregulation of CD69 in the malignant advanced tumor." (PMID 29453833, 2018).
tumor (continued). "Finally, CD8+ T cells, including activated cytotoxic T lymphocytes (CD8+CD69+), are specifically recruited into MT/ShcA2F/2F tumours." (PMID 28276425, 2017). "Given that basal levels of NK cell activation in saline treated tumor bearing mice was high with ~40–50% of NK cells degranulating and expressing CD69 this may be masking detection of obinutuzumab mediated activation." (PMID 27890931, 2017). "Furthermore, those tumor-infiltrating T cells expressed activation marker CD69, indicating that they recognized the P1A tumor antigen on tumor cells." (PMID 29123081, 2017). "However, compared with non-tumor tissues, the level of CD69 expression on CD3+CD56+ NKT-like cells in tumor tissues was significantly decreased." (PMID 27409423, 2016). "Furthermore, we found that a higher level of CD69 on tumor-infiltrating CD3+CD56+ NKT-like cells than those on circulating CD3+CD56+ NKT-like cells." (PMID 27409423, 2016). "However, the activation marker CD69 expressing on CD3+CD56+ NKT-like cells in tumors were significantly fewer than those in non-tumor tissues." (PMID 27409423, 2016). "Therefore, in order to distinguish between integrin expression induced by cellular activation or tissue infiltration, we compared the integrin-expression profiles of CD69+ cells in tumor (TIL) versus tumor-draining lymph nodes." (PMID 28018343, 2016). "Using CD69 surface expression to measure effector cell activation, we also observed that tumor cells with EGFR expression can activate EGFR-CAR-transduced NK-92 cells, with higher activation when MDA-MB-231 and MDA-MB-468 cells were used than when MCF-7 cells were used." (PMID 27050072, 2016). "For example, NK cells present in tumor-infiltrated peripheral tissues are often enriched in CD56bright CD16neg/dim NK cells; in contrast, an expansion of an unusual subset characterized by a CD56dim CD69+ CCR7+ KIR+ phenotype has been detected in tumor-infiltrated lymph nodes." (PMID 27774094, 2016). "Also, priming the human DC with supernatant of apoptotic tumor cells imprinted the DC to induce CD69+ Treg cells." (PMID 25759842, 2015). "Activation as measured by the expression of CD25, CD69 or IFNγ can be achieved by Fc receptor cross-linking, exposure to NK-sensitive tumor cells, co-incubation with mature dendritic cells, in vivo infections with bacteria such as listeria monocytogenes, among others (and data not shown)." (PMID 25101668, 2014). "Besides, T cell activation marker, CD69, was also assessed and significant downregulation of CD69+ cells was noted in tumor free mice." (PMID 23326300, 2013). "CD69 expression has been reported in infections, autoimmune diseases, and tumor infiltrates." (PMID 23119065, 2012). "Similarly, the frequency of CD69+ CD4+ cells was also significantly elevated in tdLN of high tumor-burdened animals compared to the low tumor burden group (p < 0.005; unpaired two-tailed Student’s t test)." (PMID 22674057, 2012). "In addition, we showed that, in contrast to paired blood Tregs, tumor-infiltrating Tregs display an activated phenotype, as they expressed elevated levels of CD69 and HLA-DR." (PMID 21935436, 2011). "In fact, we demonstrated that upon encountering specific antigen on tumor cell surface, human T cells harboring anti-tumor scFv-TCRζ receptors are able to undergo specific activation, including up-regulation of the early T-cell activation marker CD69." (PMID 19777065, 2009). "Moreover, it was described in a tumour model that inhibition of NF-κB in tumour cells induced an upregulation of CD69 on NK co-cultivated with these cells." (PMID 18931086, 2008). "We observed elevated percentages of CD11b+ Ly6G+ neutrophils, CD11b+ Ly6G- Ly6C+ monocytes, CD8+ CTLs, and activated CTLs (CD8+ CD69+), as well as decreased percentage of M2 macrophages upon chitosan treatment; indicative of an activation of the tumor immune microenvironment." (PMID 40860135, 2025).
tumor (continued). "Thus, in the context of combination treatment, arsenic sulfide inhibits THBS1 in tumor cells while upregulating CD69 and downregulating LAG3 in T cells, it is reasonable to surmise that arsenic sulfide modulates T cell activity to augment the efficacy of anti-PD-1 therapy." (PMID 41019041, 2025). "Within a detrimental TME, infiltrating MAIT cells display an exhausted phenotype, largely driven by tumor-associated macrophages (TAMs), which induce dysfunction through increased expression of CSF1R+ (colony stimulating factor 1 receptor), PD-L1+ (programmed cell death ligand 1), and CD69+." (PMID 40746558, 2025). "However, the roles of different T-cell types, such as CD69+ and CD69− T cells, remain unclear, particularly in relation to their location within or outside the tumor." (PMID 40361474, 2025). "In addition, we found a significantly higher proportion of terminally exhausted CD8+ T cells (Tex-term; TCF1−PD-1+CD69+) within the tumour compared to the spleen, a secondary lymphoid organ (p < 0.0001, 2way ANOVA), again consistent with what has been described in human cancer." (PMID 38986249, 2024). "Moreover, anti-PD-1 treatment did not significantly alter CD69 expression levels in CD8+T cells isolated from PY8119 Grn WT tumors, whereas depletion of tumor-derived PGRN led to a significant up-regulation of CD69 expression in CD8+T cells in response to anti-PD-1 administration." (PMID 38554213, 2024). "Moreover, PD-L1 blockade, CD4+ T cell depletion, or their combination not only increased the proportions of tumor-infiltrating CD44+CD69+CD8+ T cells but also elevated the proportions of central memory CD44+CD62L+CD8+ and effector memory CD44+CD62L−CD8+ T cells, compared with the control group." (PMID 36969495, 2023). "Additionally, an increase of CD69 on CD8 T-cells was observed in the tumor-draining lymph nodes." (PMID 37654492, 2023). "Therefore, CD69 is becoming a factor regulating anti-tumor immunity through T-cell exhaustion." (PMID 37901220, 2023). "This observed change in the PD-1/CD69 ratio could indicate a shift in the balance of activation and PD-1 expression towards the former, which could be beneficial in the context of tumor immunology, particularly in conjunction with reduced PD-L1 expression on tumor cells." (PMID 38116319, 2023). "In addition, the proportions of CD69+ or effector molecule granzyme B (GZMB)+ cells among tumour-infiltrating CD8+ T cells were higher in irradiated TRIM21-KO tumours, indicating the IR-induced activation of the CD8+ T-cell antitumour immune response in TRIM21-KO tumours." (PMID 36797289, 2023). "In addition, the supernatant levels of T cell‐derived cytokines interleukin‐2 (IL‐2) and interferon‐γ (IFN‐γ) were remarkably upregulated in B3Z T cells cocultured with RA‐pretreated tumor cells, concurrently accompanied with increased expression level of T cell activation marker CD69." (PMID 36876644, 2023). "Furthermore, we observed a twofold increase in the number of CD4+TRM cells and a sixfold increase in the number of CD8+TRM cells in the skin at the tumor rechallenge sites compared to the concurrent accumulation of many activated CD69+CD103-T cells into the skin prior to the rechallenge." (PMID 37407600, 2023). "Thus, CD69 has a double-edged effect in tumor immunity and here, we show that it may effectively predict response to PD-1/PD-L1 blockade." (PMID 36045683, 2022). "Indeed, we could detect a clear subset of CD69+CD103+ TRM-like cells in bulk CD8+ TEMs isolated from the proximal TDLNs (close to the tumor)." (PMID 36229613, 2022). "This also indirectly confirmed that CD69 might be an important tumor suppressor." (PMID 36117156, 2022). "For example, tumor TRM may share expression of CD69 with subsets of precursor and terminal TEX." (PMID 34571883, 2021).
tumor (continued). "L-selectin dependent upregulation of CD69 was seen in tumors and lymphoid organs suggesting that a ligand-expressing accessory cell is unlikely to be tumor cells but an antigen-presenting cell that matures in the tumor microenvironment and re-locates to lymphoid organs." (PMID 31249570, 2019). "In tumor microenvironment, CD69 expression may represent over-activation of lymphocytes." (PMID 31109341, 2019). "Interestingly, in mice treated with the combination TAB004 + Lip-MSA-IL-2 or TAB004 alone, we observed a significant decrease in the percent of tumor-associated CD45+ lymphocytes and of CD8+CD69+ T lymphocytes compared to tumors from mice treated with PBS or Lip-MSA-IL-2 alone (P < 0.01)." (PMID 31114758, 2019). "Thus, in the case of the tumors described herein, the consequence of CD69 expression on Tregs may be the retention of tumor-infiltrating super-suppressors thereby ensuring Treg dominance within the tumor microenvironment." (PMID 26433463, 2015). "Consistent with our findings, investigators have reported that the surface expression of CD69 and NKp46 that are either up-regulated (NKp46) or induced ex-novo (CD69) after exposure to IL-2 was not inhibited by the interaction with tumor-associated fibroblasts." (PMID 25367326, 2014). "Further, our findings of low expression of the early activation marker CD69 in blood but substantially higher in lymph nodes is also in agreement with a previous study demonstrating the enrichment of CD69+ lymphocytes in both tumour reactive lymph nodes and control lymph nodes." (PMID 22396788, 2012). "A link between NK activity and CD69 expression was suggested by the observation that, compared with WT mice, CD69−/− mice showed an enhanced NK-mediated anti-tumour response that led to greater protection and rejection of major histocompatibility complex class I low tumour cells." (PMID 18931086, 2008). "Two CD103+ resident (CD69+, CD103+, KLF2−) T cell clusters were identified and denoted as TEX and TRM populations with TEX cells mostly present in tumor-derived tissue and TRM clusters present in both tumor and noncancerous tissue." (PMID 41461987, 2026). "Collectively, these data identify a subset of tumor-restraining, pro-immunogenic lymphocytes—CD8+GzmB+, CD4+IFN-γ+, CD103+ TRM, and CD69+ memory cells—whose activation predicts favorable outcomes and treatment responsiveness." (PMID 41562715, 2026). "These analyses showed that antigen-specific, tumor-derived TPROG, TEX-like and TRM cells were more similar to each other, and distinct from CD69− and spleen-derived populations." (PMID 41461987, 2026). "As per the naive T cell experiment, barcode distribution reinforced that tumor-derived TPROG, TEX-like and TRM cells displayed a high degree of barcode overlap and were distinct from CD69− and spleen-derived populations." (PMID 41461987, 2026). "We examined cytokine secretion profiles (IL-2, IL-4, IL-6, and IFNG) from activated T cells (CD69, IL-2RA, CD38, and HLA-DRB1) to evaluate T-cell activation in the CM tumor microenvironment, revealing consistently low expression levels." (PMID 40959090, 2025). "This, in turn, recruits CXCR3+CD69+ CD8+ T cells, fostering the formation of tumor‐specific, brain‐resident TRM cells with a clonally expanded TCR repertoire." (PMID 41361844, 2025). "Intratumoral CD8+ T cells showed reduced CD69 activation marker expression but upregulated exhaustion markers PD-1 and TIM-3 compared to non-tumor tissues, while CD39 expression remained comparable between both sites." (PMID 41182407, 2025). "The upregulation of CD103, CD69, and CD49a strengthens the ability of TRM cells to settle in the tumor niche, improving their capacity to fight tumors." (PMID 39802636, 2025). "For example, the expression of CD69 and CD62L indicates NK cells' readiness for activation and tumor infiltration, which are critical for their anticancer efficacy." (PMID 40533418, 2025).
tumor (continued). "Functional validation experiments confirmed that tumor-conditioned dendritic cells upregulate ICOSL expression and promote CD8+ T-cell activation through the ICOS–ICOSL axis, as evidenced by increased CD69 and CD25 expression." (PMID 41180156, 2025). "PD-1 was uniformly expressed in CD69+ populations; however, its expression on CD69−CD4+ and CD69−CD8+ T cells in tumor tissues differed significantly between patients with and without alcohol etiology." (PMID 40361474, 2025). "The presence of CD69− T cells—particularly CD4+ and CD8+ subsets—within the TME, is potentially impacting an effective anti-tumor response that improves RFS." (PMID 40361474, 2025). "SM-102-treated groups exhibited higher CD69 levels in CD8+ and CD4+ T cells than PBS and MC3 controls, indicating a preferable status of T cells for tumor killing." (PMID 41041043, 2025). "The potency of 2xAARE-YB-CAR-Jun-T cells is likely attributable to a substantial increase in the number of tumor-infiltrating activated CAR-T cells, as evidenced by elevated expression of the activation marker CD69." (PMID 40335738, 2025). "Significantly higher percentages of CD69+, CD107a+ and IFN-γ+ tumor-infiltrating CD8+ T were detected in NPc-Rel-treated mice compared to the PBS group." (PMID 40134427, 2025). "CCA with a higher proportion of CD69+CD103+CD8+ TRM cells showed a greater number of TIL infiltrates, higher PD‐L1 expression on the tumor, and higher expression levels of the T‐cell‐inflamed gene signature." (PMID 39802636, 2025). "In contrast, activation markers CD39, CD69, and PD-1 were strongly upregulated on both CD8 and CD4 T cells in the tumor compared to the blood for all patients." (PMID 39918475, 2025). "Anti‐PD‐1 therapy systematically inhibited the expression of PD‐1 in T cells from samples including tumour, blood and bowel wall and significant down‐regulation of CD39 and CD69 in ILC and T cell subsets in TME was also observed." (PMID 39934971, 2025). "When coincubated with tumor cells, γδ CAR-T cells presented increased expression levels of CD69, TNF-α and granzyme B." (PMID 39939816, 2025). "Here we show that experimental downregulation of KLF2 in vaccine activated CD8+ T cells led to the accumulation of intratumoral phenotypically defined CD69+CD103+ and CD69+CD49a+ Trm, which correlated with enhanced inhibition of tumor growth." (PMID 40162209, 2025). "The enhanced systemic response correlated with increased immune activation in tumor-draining lymph nodes, specifically a higher fraction of activated CD8+ T cells (CD69+) in carbogen-treated mice." (PMID 40568078, 2025). "Tumor resident Trm in mice and humans are, therefore, generally monitored using phenotypic markers like CD8+CD69+CD103+ or CD8+CD69+CD49a+ T cells." (PMID 40162209, 2025). "However, we characterized further the tumor-infiltrated NK cells, and we observed an increase of cytotoxic mature NK cells, as shown by the degranulation marker CD107a and NK cell activation markers (CD69+ and NKG2D+/NKp46+) in mice treated with AU-15330 and cisplatin." (PMID 39813356, 2025). "EphA2 overexpression in the tumor significantly downregulated surface activation markers CD44, CD69, and CD25 on CD8+ T cells via flow cytometry." (PMID 40867322, 2025). "Subsequently, we found diminished level of CD8+T cells in Vcp-overexpressing tumor, with these CD8+T cells exhibiting visibly lower levels of cytokines and activation markers CD69, CD25, CD4433 compared to controls." (PMID 39848960, 2025). "Gene expression analysis revealed higher levels of activation, cytotoxicity, and memory markers (e.g., CD69, PRF1, TNF, KLRB1, and NCR3) in iMRAS-activated CAR-iNKT cells, correlating with their enhanced tumor-killing potential." (PMID 40297706, 2025). "Increased CD103N cell with lower activation and exhaustion levels was supposed to be responsible for the reduced CD69 levels and comparable CD39 levels in intratumoral CD8+ T cells in pMMR CRC as compared to non-tumor tissue." (PMID 41182407, 2025).